IL10 (interleukin 10)
Diseases named in the same sentence as IL10 in open-access papers (continued):
Sharing a sentence is not in itself a finding about the gene and the disease.
tumor (continued). "Tumor associated macrophages in the resting phase secrete immune-suppressive cytokine IL-10, while during activation by lipopolysaccharide (LPS), they secrete proinflammatory cytokines IL-1β, IL-6 and TNF." (PMID 32120819, 2020). "Various interleukins expressed by TAMs are also associated with tumor progression and prognosis, including IL-6, IL-10, CCL5, and CXCL8." (PMID 32268527, 2020). "According to a generally accepted model, IL-10 is considered an anti-inflammatory and pro-oncogenic cytokine, associated to T regulator lymphocyte increase and M2 polarization of tumour associated macrophages." (PMID 32397484, 2020). "A study of patients with ovarian carcinoma demonstrated that the tumor-infiltrating follicular regulatory T (Tfr) cells exhibit significantly upregulated IL-10 expression, which is negatively associated with IFN-γ secretion in CD8+ TILs." (PMID 32117960, 2020). "Regarding the expression of cytokines, higher IL-10 tumor levels were associated with a lower frequency of extranodal disease at diagnosis (p = 0.03)." (PMID 32913559, 2020). "Tumor cells, macrophages, DCs and Tregs have all been implicated in the production of IL-10 in the TME." (PMID 32121071, 2020). "Here, they identified tumor-associated macrophages (TAMs) as a dominate population in tumors, with high baseline Arginase I and IL-10 expression, and low iNOS activity, when stimulated with LPS/IFN-γ." (PMID 33329545, 2020). "These bone marrow-derived cells cause immunosuppression of the tumor microenvironment not only by humoral factors such as IL-10 and TGFβ, but also by ICMs, extracellular vesicles, and nutrient consumption." (PMID 32707672, 2020). "Accumulating evidence has suggested that, upon entering the tumour environment, M-MDSCs quickly differentiate into tumour-associated macrophages (TAMs), leading to enhanced IL-10 secretion and impaired T-cell response." (PMID 32265505, 2020). "The TME is usually highly immunosuppressed due to the secretion of tumor-derived growth factors (VEGF, TGFβ), or macrophage-derived IL-10, with significant infiltration of myeloid-derived suppressor cells (MDSCs) and tumor-associated macrophages (TAMs)." (PMID 32774773, 2020). "TNF-α, IL-6, and IL-17 have known roles in tumor growth and promotion; IL-6 and IL-10 are produced by tumor-associated macrophages and create conditions of immune suppression and angiogenesis." (PMID 32156252, 2020). "Tumor-derived cytokines with immunosuppressive activities, such as IL-10 and IL-4, are able to convert tumor-associated macrophages (TAMs) to polarized type 2 (M2 macrophages) that promote cancer progression." (PMID 33003428, 2020). "The Wnt/β-catenin activation in tumor cells has been variously implicated in the suppression of DC functions by paracrine IL-10 production and the downregulation of CCL4, a chemokine responsible for the recruitment of CD103+ cDC1s." (PMID 32486257, 2020). "In contrast, the proportion of IL-10-producing regulatory B cells (Bregs) in HPV-associated tumor tissues was comparable to the levels of Bregs in control tonsils, indicating that Bregs do not accumulate in the tumor microenvironment of HPV-associated HNSCC." (PMID 33042814, 2020). "Tumor cells often secrete a high amount of IL10, and increased serum concentration of IL10 found to be associated with simultaneous immunostimulation and immunosuppression in different types of cancer." (PMID 32219066, 2020). "For example, IL-4 synergizes with IL-6 and IL-10 to promote cathepsin secretion in tumor-associated macrophages via UPR activation, resulting in cancer cell invasion." (PMID 32085512, 2020). "For example, the tumor-suppressive growth arrest-specific transcript 5 (GAS5) lncRNA was reported to be associated with the expression of VEGF-A and IL-10 in the tumor cells." (PMID 32083005, 2020). "Of note, PDAC is associated with higher levels of TGF-β and IL-10, locally in the tumor tissue and systemically in the blood, supporting immune evasion." (PMID 33022971, 2020).
tumor (continued). "Tumor-associated macrophages (TAMs) are recruited by tumor cells via cytokines such as CSF-1 and IL-10 and converted into M2 macrophages, which have anti-inflammatory, angiogenic and tumor-promotive effects." (PMID 32514351, 2020). "Loss of classical HLA class I was associated with HLA-G upregulation.IL-10 expression coincided with HLA-G upregulation.NK cells infiltration was associated with loss of HLA class I on tumor cells." (PMID 33425752, 2020). "In contrast to their wild-type K-ras cousins, tumor cells bearing K-ras mutations induce suppressive Tregs by enhancing the secretion of IL-10 and TGF-β." (PMID 32039025, 2019). "MDSCs are associated with inflammation-induced tumor progression, as they are activated by pro-inflammatory IL-1β that subsequently induces a tumor-promoting IL-10-dominated environment and an anti-inflammatory (M2) macrophage response." (PMID 31396229, 2019). "Several molecules, including IL-10, IL-32, epidermal growth factor and growth arrest-specific gene 6, have been associated to the tumour-promoting function of TAMs." (PMID 31480312, 2019). "In WSC, we identified an association between the plasmatic ANGPTL-4, IL-15, and IL-10 in tumor and IL-15 in MES." (PMID 31741709, 2019). "Along with tumor cells, tumor-associated macrophages (TAMs) produce IL-10, which abrogates the anti-tumor effects mediated by cytotoxic T cells." (PMID 30814315, 2019). "M2-like macrophages are in general major producers of IL-10, which was also supported by our data showing a strong correlation between IL-10 and the tumor-associated macrophage marker CD163 in both patient cohorts." (PMID 30879106, 2019). "On the other hand, in weight stable patients, who had a low ANGPTL-4 levels in plasma and tumor, it was observed an association of this protein to IL-10 and IL-15, anti-inflammatory and anti-tumorigenic factor." (PMID 31741709, 2019). "Conversely, the M2 macrophages are associated with Th2 cytokines, such as IL-4, IL-10, IL-13, and are implicated in anti-inflammatory responses and tumor-promoting signals." (PMID 31547048, 2019). "On the contrary, the existence of fractions of CTLs that express FOXP3 secrete immunosuppressive interleukin (IL)-10 and co-express molecules associated with anergy, exhaustion, or unresponsiveness in tumor-infiltrating lymphocytes was reported." (PMID 31016433, 2019). "In our data, we found the CD68+IRF8+, CD68+CD206+, and CD68++CD163+ macrophages to be co-localized in the same tumor and were correlated with the increase of IL-1-, IL-6-, and IL-10-associated pathways, respectively." (PMID 31477692, 2019). "For example, severe hypoxia induces tumor cells to release IL10 and TGFβ which promote differentiation of tumor associated macrophages (TAM) to M2 macrophages that shows immunosuppressive functions." (PMID 31382593, 2019). "Positive associations of ANGPTL-4 with IL-10 and IL-15 and IL-15 in the tumor and the mesenteric adipose tissue were observed in WSC group." (PMID 31741709, 2019). "In contrast, the M2 subset is characterized by diverse immunosuppressive activity and includes wound-healing macrophages, IL-10-secreting regulatory macrophages, and tumor-associated macrophages that suppress anti-tumor immunity." (PMID 31662766, 2019). "IL‐12‐producing M1 phenotype is associated with antiparasitic and tumor‐resistance capabilities, and IL‐10‐producing M2 phenotype is related to wound healing, immune regulation, and resolution of inflammation." (PMID 29877619, 2019). "IL-10 was considered as a switch from tumor-promoting inflammation to antitumor immunity, and deficient IL-10 signaling developed tumors spontaneously and at high rates." (PMID 32010645, 2019). "The growth of primary tumours and metastases is strongly inhibited in C3-deficient mice and is associated with increased numbers of IFNγ+/TNFα+/IL10+ CD4+ and CD8+ T cells." (PMID 30841875, 2019).
tumor (continued). "In SKOV-3 cells, PD-L1 was variably found in the surface and cytoplasm, and its expression was correlated with high levels of TNF-α, IL-10, and IL-6 released from tumor-associated macrophages (TAMs)." (PMID 31861351, 2019). "Similar to TAMs, it is likely that MDSCs are stimulated by a variety of soluble factors, such as GM-CSF, VEGF, TNF-α, PGE2, IL-1β, IL-6, and IL-10, which are secreted by tumor and infiltrating immune cells, as well as tumor-associated fibroblasts." (PMID 31428574, 2019). "For example, elevated concentrations of systemic IL-10 are associated with a poor prognosis, but paradoxically, high levels of tumor IL-10 are associated with a better prognosis." (PMID 31174326, 2019). "In the present study, we showed how NLGP modulates tumor-associated MSCs by reducing their IL-10 secretion that ultimately results in reduced phosphorylation of STAT3 leading to enhanced transcription of cystathionase in DCs." (PMID 31547863, 2019). "Because IL-10 converts macrophage to tumor-associated macrophages, it is possible that NNKTL cells educate macrophage to be tumor-supportive." (PMID 31041299, 2019). "In mouse models, the immunosuppressive or anti-tumor roles of IL-35 have been linked to its ability to induce the expression of IL-10 and the immune checkpoints LAG3, TIM3, and PD1 in T cells, leading to T cell exhaustion and decreased anti-tumor immunity." (PMID 31316915, 2019). "Tumor secrets various immune suppressive cytokines such as VEGF, IL-6, and IL-10 to promote the accumulation of heterogeneous populations of tumor associated macrophages (TAMs), myeloid-derived suppressor cells (MDSCs), and regulatory T cells." (PMID 31639056, 2019). "The recruited neutrophils via CXCL12-CXCR4 axis secrete IL-10 that suppresses cytotoxic T cell function on tumor cells, which then causes anti-VEGF therapy resistance in SL4 and CT26 colorectal carcinoma." (PMID 31474975, 2019). "For example, tumour-associated macrophages (TAM) release interleukin (IL)-10 and prostaglandin E2 to suppress antitumor response." (PMID 30824727, 2019). "We found that the immune-suppressive and tumor-promoting effects of these TH cells are linked, at least in part, to their expression of IL-10." (PMID 30926808, 2019). "This is associated with CD163 expression, IL-10 production, angiogenesis and tissue remodeling in murine models of various cancers- all of which can contribute to increased tumor growth and metastasis." (PMID 31824850, 2019). "Elevated plasma levels of IL-8 and IL-10 were identified as risk factors for increased tumor size (diameter ≥5 cm)." (PMID 29742685, 2018). "In the current study, a strong association was found between high IL-10 and lower tumour grade, lower NPI level, positive ER and PgR status, negative Her-2 expression as well as with the non-TN type." (PMID 29256156, 2018). "High IL-10 expression was, however, significantly associated with lower tumour grade (P < 0.001), low NPI value (P < 0.001), positive ER (P < 0.001), positive PgR (P < 0.001), negative Her-2 (P = 0.003) as well as non-TN status (P = 0.003)." (PMID 29256156, 2018). "While a variable capacity to secrete IL-6, IL-1β and TNF-α is shared by differentially polarized macrophages, an IL-12 low/IL-10 high phenotype is the hallmark of M2 macrophages, which are known to promote tumor growth." (PMID 29454317, 2018). "Tumor-Associated Macrophages (TAMs) express high levels of B7-H4, which is attributed to the presence of IL-6 and IL-10." (PMID 29988281, 2018). "Expression of Il4, Il10 and Il13, which represent cytokines commonly associated with alternative macrophage activation, was undetectable in 4T1 tumours." (PMID 30054470, 2018). "In order to verify that the upregulation of PD-L1 on Stat1 deficient macrophages, increased IL-10 secretion and impaired Irf1 expression also impairs the killing function of Stat1 deficient macrophages, we next isolated CD11b+ cells from tumor bearing lungs." (PMID 30647851, 2018).
tumor (continued). "A previous study reported that NDRG2 can inhibit IL-10 expression, which plays an important role in tumor-associated immune response by modulating SOCS3 and STAT332." (PMID 29445150, 2018). "In contrast to anti-IL-10 Abs, shIL10–3 LVs were able to induce antitumor response and caused tumor growth inhibition at the level of 71.5%." (PMID 29954431, 2018). "Many of these molecules including vascular endothelial growth factor(VEGF), platelet derived growth factor (PDGF) and interleukin-10 (IL-10) are associated with tumor growth, poor prognosis and metastasis." (PMID 29783929, 2018). "In NSCLC, IL-10 overproduction at the tumor site has been implicated in tumor-mediated immunosuppression, enhanced angiogenesis and serum IL-10 appears to be an indicator of poor prognosis." (PMID 29732034, 2018). "On the other hand, IL-10 has immunosuppresive effects and also is associated with tumor progression such that tumor IL-10 levels correlate with disease severity." (PMID 29721190, 2018). "The transcription factor STAT3 is known to cause IL10-mediated suppression of both STAT1 as well as STAT1-mediated induction of the anti-tumor cytokine IL12." (PMID 30041669, 2018). "Tumor-associated macrophages often exhibit an immunosuppressive M2 phenotype by expressing interleukin 10 (IL-10), arginase-1, and TGF-β1." (PMID 29903994, 2018). "Among the NF-κB subunits, NF-κB1/p50 is the most abundantly found subunit in tumor-associated macrophages that plays a critical role in suppressing anti-tumor responses by decreasing IL-12 production and increasing IL-10 level." (PMID 29889863, 2018). "Another study associated the increased expression of IL-10 in tumour cells with a more aggressive tumour phenotype." (PMID 30539028, 2018). "The secretion of the first molecule by cancer cells and cancer associated cells is a well know mechanism of tumor evasion, and IL-10 as well as IL-4 are potent immunosuppressive cytokines." (PMID 28331617, 2017). "To explore the putative retraining of the TAMs in tumor tissues, we detected the expressions of immune factors and those associated with tumor angiogenesis, such as IL-10, TGF-β, and VEGF." (PMID 28243242, 2017). "IL-10 deficiency leads to stimulation of inflammatory responses, inflammatory bowel disease and spontaneous tumor development." (PMID 28333114, 2017). "IL24, also known as melanoma differentiation-associated gene-7 (MDA-7), is a member of the IL10 cytokine family, and has been identified as an important immune mediator as well as a tumor suppressor." (PMID 28109288, 2017). "Th1 cytokines, including IFN-γ, IL-2, and TNF-α, enhance the cytotoxicity of CIK cells, whereas Th2 cytokines like IL-6 and IL-10 is associated with tumor immune escape." (PMID 28404886, 2017). "For immune escape, the extrinsic pathways, by recruiting and activating immunosuppressive tumor-associated TAMs, Tregs, and MDSCs via IL-10/TGF-β/PGE2/CCLs/CXC chemokine ligands-regulated mechanisms, are important to defeat immune surveillance." (PMID 28143527, 2017). "IL-10 is one of the Th2-associated cytokines and induces an immunosuppressive microenvironment such as infiltration of tumor-associated macrophages, thus inhibiting the anti-tumor immune reaction." (PMID 29100307, 2017). "Taxa in the Clostridium XIVa cluster have been shown to induce the production of the anti-inflammatory cytokine IL-10 by T regulatory cells and inhibit the proinflammatory NF-κB pathway, implicated in tumor cell apoptosis." (PMID 28443082, 2017). "Tumour associated T regulatory cells and tumour associated antigen presentation cells, such as dendritic cells and macrophages, have been shown to produce IL-10." (PMID 28810829, 2017). "IL-10 is a cytokine that modulates immune responses, causing suppressive regulatory T cell differentiation that contributes to tumour cell proliferation." (PMID 28381274, 2017).
tumor (continued). "In the tumor microenvironment, tumor-associated macrophages (TAMs) are “polarized” into M2 mononuclear phagocyte-like cells by various cytokines (IL-4, IL-10, and transforming growth factor β (TGF-β))." (PMID 28218682, 2017). "We therefore evaluated the prognostic value of tumor-associated macrophages in AITL because our data showed a significant association of high serum IL-10 with poor OS in AITL." (PMID 29100307, 2017). "Activation of S1PR4 signaling on human and murine tumor-associated macrophages (TAMs) by apoptotic tumor cell-derived S1P leads to the production of tumor-promoting cytokines, including IL-6 and IL-10." (PMID 28848247, 2017). "Consistently, the tumor tissue showed reduced expression of Il10, an M2 macrophage-associated gene, and increased expression of Il12, a marker gene for the M1 macrophages." (PMID 27909985, 2017). "Regulatory T cells (TRegs) and tumor-associated macrophages (TAMs) within the tumor microenvironment contribute to elevated IL-10 production, which functionally impairs infiltrating T effector cells." (PMID 26861381, 2016). "Tumor-associated macrophages (TAMs) can promote tumor progression by suppressing effector T cell responses through the production of anti-inflammatory cytokines such as IL-10 and TFGβ." (PMID 27153100, 2016). "A variety of cytokines secreted by Bregs have been implicated in the suppression of anti-tumor immunity including IL-10, IL-35, IL-6, and TGF-β." (PMID 27437104, 2016). "Our data suggest that IL-10 is closely linked to tumor-associated CD4+ populations expressing either IFN-γ or IL-17A, whereas the presence of TGF-β appears to be of secondary importance." (PMID 27075020, 2016). "Engagement of truncated O-glycans by lectin receptors on tumor-associated macrophages likewise promotes production of anti-inflammatory cytokines, such as IL-10 and TGFβ." (PMID 27153100, 2016). "Interleukin-10 (IL-10), encoded by the IL-10 gene located on chromosome 1q31–32, is a potent regulator of anti-tumor immune responses." (PMID 27995011, 2016). "In dissecting the potential immune regulatory role of the TME IL10 expression we examined the effects of immunizing tumor bearing mice to VV encoding the lacZ gene with a readout of antibody response to the beta-galactosidase protein." (PMID 28191451, 2016). "High production of IL-10 is also a characteristic feature of tumor-associated/M2 macrophages, adapted to suppress immune responses against tumors." (PMID 27388564, 2016). "It has been shown that patients with OSCC have increased levels of salivary IL-10 and high expression of this cytokine in tumor cells has been associated with poor prognosis." (PMID 27536540, 2016). "These cytokines are involved in the immunosoppression of tumour-specific immune responses and are associated with the induction of IL-10-producing Treg cells in response to tumours." (PMID 26795765, 2016). "Increased tumor IL-10+ Breg frequency was also associated with increased FoxP3+ Treg infiltration and reduced survival." (PMID 27437104, 2016). "Surprisingly, abrogation of IL-10 led to the promotion of tumor-associated Nrp-1 expression on CD4+ T cells only after TGF-β Ab treatment." (PMID 27075020, 2016). "Third and most importantly, our data demonstrate that IL-10 deficiency impairs Treg-derived Nrp-1 functions to promote Th1 and Th17 immunity, suggesting that Nrp-1 is a critical molecule in tumor pathogenesis." (PMID 27075020, 2016). "Treatment of tumor-bearing WT mice with oxaliplatin was associated with emergence of a tumor-infiltrating CD19+CD138+IgA+ plasma cell population that expressed IL-10, PD-L1, phosphorylated Stat3, and Fas-L." (PMID 27437104, 2016). "Our data showed a clear decrease in Nrp-1 obviously in IL10-deficient tumor-bearing mice, and the number of CD4+Foxp3+Nrp-1+ T cells obtained from the spleen was significantly decreased in IL10−/− B16/F10 mice based on flow cytometry analysis." (PMID 27075020, 2016).